EGFR (epidermal growth factor receptor)
Diseases named in the same sentence as EGFR in open-access papers (continued):
Sharing a sentence is not in itself a finding about the gene and the disease.
tumor (continued). "Our study extends the current paradigm to imply that patients with KRAS-, BRAF- or PIK3CA-mutant tumours may all derive limited benefit from treatment with EGFR mAb, and that BRAF mutations in particular account for a measurable fraction of patients whose KRASWT tumours do not respond to cetuximab." (PMID 19603024, 2009). "Interestingly, AR localisation was not confined to the cytoplasm of tumour epithelium as might be expected of a secreted glycoprotein (which acts as a ligand for EGFR)." (PMID 19558693, 2009). "Although we would assume that tumors overexpressing EGFR would respond well to anti-EGFR therapy, studies have demonstrated that the level of EGFR expression does not have any impact on tumor response rates as a significant number of EGFR-positive tumors could be resistant to Erbitux." (PMID 19878607, 2009). "Indeed, one patient did not respond to MoAbs by virtue of the absence of PTEN expression limited to the metastatic lesion in a context of a molecular profile proficient to MoAb response (EGFR CNG and no additional alterations in EGFR downstream pathways in both primary tumour and metastasis)." (PMID 19293803, 2009). "Thus, although the tumor could be visualized, high levels of background activity were observed, and more importantly, the EGFR specific tumor uptake was not evaluated." (PMID 18991714, 2008). "Interestingly, patients with tumours that do not overexpress the EGFR but overexpress cortactin had a 5-year overall survival of 22%, similar to patients with tumours that overexpress both EGFR and cortactin." (PMID 18268492, 2008). "One of the possible explanations for the presently observed supra-additive anti-tumour activity may lie in an optimal ‘vertical blockade’ of VEGF pathway not obtained by either agent alone bearing in mind that EGFR targeting leads to inhibition of VEGF tumour secretion." (PMID 18577994, 2008). "Although it is possible that signals from the CaR or other G-protein receptors might result in high levels of EGFR activity in the RWGT2 line, the lack of robust EGFR phosphorylation in the HARA tumours suggested transactivation did not account for increased PTHrP gene expression in this model." (PMID 17533397, 2007). "In addition, response to cetuximab has been observed also in patients with EGFR-negative tumours." (PMID 17940504, 2007). "When investigating outcomes, such as response to anti-EGFR therapy, it may be more beneficial to choose a cutoff score leading to high sensitivity rather than specificity for tumour response to select the greatest number of potentially responsive candidates for treatment." (PMID 17311026, 2007). "Signaling from mutant but not wild-type (WT) EGFR was shown to activate anti-apoptotic pathways, and small interfering RNA-mediated down-regulation of mutant EGFR resulted in the death of these cells, but the mechanisms for tumor cell killing were not examined." (PMID 17973573, 2007). "In conclusion, autocrine AREG stimulation of the EGFR may serve as the intrinsic factor that drives high levels of PTHrP gene expression in the RWGT2 line, whereas this pathway appears to play a secondary role in the extrinsic activation of the gene in HARA tumours by host factors." (PMID 17533397, 2007). "While the predictor seems to have misclassified one tumor that harbors mutant EGFR, we note that others have reported that cell lines with activating EGFR mutations are also insensitive to EGFR TKI, and our predictive models may have identified a tumor that will not respond to treatment." (PMID 17096850, 2006). "This is likely to be due to the mechanism of action of the EGFR inhibitors, which target the tumour cells directly, whereas VEGF inhibition can be anticipated to elicit a cytostatic effect and therefore combination with conventional approaches may be required in order to eradicate the tumour." (PMID 15928655, 2005).
tumor (continued). "Interestingly, although there was a spectrum of dose-dependent antitumour activity ranging from dramatic tumour regression to de novo resistance when gefitinib was tested in multiple human tumour xenograft studies, the level of EGFR expression did not predict tumour response." (PMID 14760365, 2004). "In addition, when genetic alterations linked to anaplasia were pooled (chromosome 10 loss, chromosome 9p loss, EGFR amplification, p16 deletion, PTEN mutation and telomerase reactivation), nongrowing tumours showed significantly fewer alterations than growing tumours (P=0.029)." (PMID 14676814, 2003). "The current paper addresses the safety of combining EGFR, ALK, and BRAF/MEK inhibitors with RT, regardless of (solid) tumor histology." (PMID 41759225, 2026). "Notably, hypoxic tumor cells with constitutive and high EGFR activation (CAL-27 and HN30 cells) appear to employ some previously unknown antagonistic mechanisms to bypass the inhibitory effect of ubiquitination-mediated degradation by blocking the binding of Cbl/Grb2 to EGFR." (PMID 40940319, 2025). "CK5 and vimentin were strongly expressed in tumor cells within the PDX#1, #2, and #3 tumor tissues, while EGFR was highly expressed in PDX#1 and #2 tumor tissues, but not in PDX#3, consistent with IHC results from patient tissues." (PMID 40551232, 2025). "Importantly, EGFR and EpCAM exhibited no detectable signal in BM samples alone, highlighting their high specificity for cancer cells and demonstrating the sensitivity of our nested qPCR approach, particularly when 5 or more tumor cells were spiked into the sample." (PMID 40073025, 2025). "Moreover, low tumor mitotic activity was associated with better prognosis in LUAD subgroups with EGFR mutations or pan-negative (no oncogenic alteration in genes including KRAS, EGFR, BRAF, ERBB2, PIK3CA, ALK, and ROS1) but not in those with KRAS or BRAF mutations." (PMID 41404730, 2025). "Second, by simultaneously engaging both LGR5 and EGFR, the antibody facilitates rapid endocytosis and degradation of EGFR in LGR5-positive tumor cells—a mechanism not observed in cetuximab." (PMID 41375018, 2025). "Despite numerous efforts to target EGFR, commonly dysregulated in GBM, targeted therapeutic approaches against EGFR have not achieved the same degree of success as seen in other tumour types, particularly when compared to non-small cell lung cancer (NSCLC)." (PMID 40227788, 2025). "Our results indicate that hypoxia-induced EGFR phosphorylation does not trigger Akt or ERK activation but instead leads to the activation of STAT3, which in turn induces autophagy in tumor cells." (PMID 40940319, 2025). "Although some tumors were able to regrow after EGFR TKI treatment regardless of the HDAC inhibitor co-treatment, the combination was able to prevent tumor regrowth more efficiently than the single-agent drugs." (PMID 39747003, 2025). "The constructs inhibited the migration and proliferation of EGFR-overexpressing U2OS osteosarcoma cells and induced enhanced tumor growth reduction in vivo, compared with non-targeted micelles." (PMID 39940134, 2025). "There is a negative correlation between AJAP1 and EGFR expression: as AJAP1 decreases, EGFR activity increases, promoting aggressive tumor behavior." (PMID 39936963, 2025). "A non-mitogenic epidermal growth factor receptor (EGFR) ligand is bound to the siRNA, improving tumor-specific delivery, especially to tumors with different EGFR expression levels." (PMID 40805153, 2025). "Although our study suggested the involvement of EGFR and MAPK signaling pathways in neoplasia development, this was not shown in detail and needs further research." (PMID 40732668, 2025). "Through isoform‐specific overexpression and depletion assays in murine and cellular models of EGFR‐mutant LUAD, it is revealed that RAC1B, but not RAC1A, promotes LUAD cell proliferation and tumor growth." (PMID 40548642, 2025).
tumor (continued). "Clinical and preclinical data indeed show that single or dual-agent antagonism against EGFR and/or MET receptor does not prevent tumor progression [24,34,]." (PMID 41115375, 2025). "The assay reliably detected EGFR alterations over a VAF range from 1.7 to 89.2%, and the failure rate of samples with low tumor cell content (20–30%) was not higher than for samples with higher tumor cell content (≥40%)." (PMID 40299437, 2025). "NGS is primarily applied in advanced non-squamous NSCLC, where tumor NGS testing is routinely recommended owing to the presence of numerous actionable genetic alterations, including EGFR, ALK, and ROS1, which can be targeted with specific therapies." (PMID 41515905, 2025). "LIPTAC-DDC exhibited minimal toxicity to cells without EGFR expression, further highlighting that LIPTAC specificity stems from the tumor antigen-binding domain." (PMID 40661577, 2025). "In our analysis, although we sampled only a fraction of the tumor, the similar cell age estimated for MDM4+/EGFR+ and MDM4+/PDGFRA+ clones suggested that neither of these clones gained selective advantage during tumor growth." (PMID 38724668, 2025). "Our data suggest that KI suppresses EGFR signaling in SGC cells, but co-treatment with cetuximab did not enhance the anti-tumor response of KI." (PMID 40508009, 2025). "No group differences were seen in contrast-enhancing tumor volume, T1w subtraction map values, and qT2*, nor in clinical variables such as sex category, MGMT status, and EGFR status." (PMID 40227555, 2025). "EGFR-inhibitors in any line were used in approximately 80% of patients eligible to intensive therapy, irrespective of sidedness in RAS&BRAF wild-type tumours in line with the Swedish guidelines." (PMID 40437037, 2025). "Unlike SPINK 1 and 6, which promote oncogenesis through EGFR signalling, SPINK 7 counteracts tumor progression by enhancing genomic stability and reducing cellular proliferation." (PMID 40872585, 2025). "None of the analyzed variables (age, sex, histology, stage, EGFR, KRAS) were found to display a significant correlation with IDO-1 positivity in tumor and immune cells." (PMID 40475772, 2025). "In vivo, FH-EB02 treatment significantly inhibited tumor growth in CDX and two PDX mouse models bearing tumors coexpressing EGFR and B7H3, but showed no efficacy in PDX models expressing EGFR alone." (PMID 41291854, 2025). "While robust urothelial basal-cell stratification (CK5/EGFR/CDH3) typical of Uro tumors was absent, scattered CK5-positive cells were localized at the tumor-stroma interface, which is how more aggressive Urothelial-like tumors typically present." (PMID 40605119, 2025). "None of the analyzed variables (age, sex, histology, stage, EGFR, KRAS and PD-L1 status) were found to display a significant correlation with IDO-1 positivity in tumor and immune cells." (PMID 40475772, 2025). "A modest anti-tumor effect was further described upon dual inhibition with trastuzumab and afatinib, even for ERBB2-amplified tumors lacking an EGFR amplification." (PMID 38611014, 2024). "No tumor DNA was detected in plasma; however, EGFR L858R and ERBB2 amplification (copy number 21.36) were found in tumor tissue." (PMID 38920723, 2024). "Afatinib monotherapy did not reduce tumor growth in any of the models tested except for LX1042, a PDX derived from an EGFR-mutant adenocarcinoma that transformed to SCLC on targeted therapy." (PMID 39080761, 2024). "EGFR ranked in the top five kinases for the PDAC lines but was absent in the CAF model, making it a potential tumor-specific target." (PMID 39221276, 2024). "The majority of LUAD patients succumb to tumor metastasis, therapeutic resistance including EGFR-TKI treatment, and relapse of disease, rather than their primary tumor." (PMID 38872157, 2024).
tumor (continued). "Some noticeable genes with SVs were EGFR (three tumors in HPV positive and one tumor in HPV negative group), CCND1 (three tumors in each group), and PTEN (one in each group)." (PMID 38898085, 2024). "Furthermore, distinct copy number alterations such as EGFR or ERBB2 gene amplification could be ascertained by inspecting copy number profiles in conjunction with morphology, revealing both a high likelihood for a particular tumour type and potentially providing additional predictive information." (PMID 38576030, 2024). "Unlike prior EGFR-TKI generations, osimertinib selectively and irreversibly binds to EGFR-mutants inhibiting downstream signaling pathways and ultimately preventing tumor cell proliferation while promoting apoptosis." (PMID 39202551, 2024). "Nevertheless, these results suggest that the primary tumor location may not be the sole determinant and support the notion that primary tumor location serves as a clinical surrogate marker reflecting the intricate molecular landscape of primary resistance to anti-EGFR antibodies." (PMID 38347302, 2024). "Targeting AG4 with EGFR BATs at the maximum feasible dose of 80 × 109, with or without TMZ was safe and induced significant anti-tumor-specific immune responses." (PMID 38263486, 2024). "Correlation of EGFR expression with DCIS type, DCIS grade, tumor location, and presence or absence of comedo necrosis." (PMID 39439618, 2024). "This study shows that a total of 80 × 109 EGFR BATs is safe without cytokine release syndrome (CRS) and induces anti-tumor immunity." (PMID 38263486, 2024). "Accordingly, in PC tissues expressing EGFR and which are nonresponsive to erlotinib treatment, ARNTL2 induction reversed tumor insensitivity and increased the antitumor effect of erlotinib." (PMID 38459558, 2024). "We use in vitro measurements of EOC tumour cell and T cell responses to chemotherapy, PDT, and epidermal growth factor receptor targeted PIT as inputs to a mathematical model of non-linear tumour and immune effector cell interaction." (PMID 39261715, 2024). "Additionally, the tumor microenvironment can impact EMT and therapeutic resistance, and the use of in vitro or xenograft models in immunodeficient mice may not accurately mimic the tumor microenvironment observed in patients who have developed acquired resistance to EGFR inhibitors." (PMID 39227379, 2024). "Regardless of the location of tumor development, resistance to treatment involves multiple mediators such as extracellular signal-regulated kinase (ERK), PI3Kα, EGFR, and VEGF." (PMID 38391974, 2024). "For the evaluation of the tumor targetability of iQDMs, two different cell lines, MDA-MB-453 as EGFR-negative and LS174T as EGFR-positive one, were used." (PMID 38892434, 2024). "The study showed 76%of tumor samples were negative for PD-L1 expression, and the data suggest that the activity of immune checkpoint inhibitors (ICIs) may be impaired in NSCLC with mutations in the EGFR ex20ins, EGFR ex20ins mutations have reduced efficacy with ICIs." (PMID 38774882, 2024). "Levels of cytosolic EGFR and phosphorylated EGFR were elevated in TAD mutant tumors regardless of tumor stage." (PMID 36977662, 2023). "In the first clinical trial of EGFRvIII-directed CAR T cells for GBM, a significant decrease in EGFRvIII expression was demonstrated in almost all patients in which tumor-infiltrating CAR T cells were detected, but not in wild-type EGFR." (PMID 37165457, 2023). "We observed comparable inhibition of the EGFR signaling network by WSD-0922 and erlotinib in flank tumor models, where BBB considerations are not pertinent, and in intracranial tumors." (PMID 37324218, 2023). "Western blot analysis of the tumor samples further confirmed that panobinostat treatment increased the expression of HER3, but not EGFR or IGF-1R." (PMID 37537339, 2023).
tumor (continued). "In turn, EGFR, IGF1 and MAPK1 mRNA expression levels were significantly decreased, while RHOA mRNA expression was not significantly downregulated in tumor tissues." (PMID 36882618, 2023). "LLPS of NONO has been shown to enhance the recruitment of EGFR to the COX-2 promoter, resulting in increased COX-2 expression and promoting tumor progression." (PMID 37580790, 2023). "For instance, Pembrolizumab has significantly improved the 5-year survival rate of advanced NSCLC patients and has been approved for first-line treatment in patients with PD-L1 tumor proportion score (TPS) ≥1% and without EGFR/ALK gene alterations." (PMID 38204755, 2023). "In contrast, tumor-stroma interactions were not correlated with expression levels of EGFR or EGBB3, which are solely engaged in EGFR-mediated PIP3 activation." (PMID 36647832, 2023). "Especially the subgroup of 121 patients who were pre-treatment-naive (no systemic anti-tumor treatment, including chemotherapy and/or antibodies such as anti-VEGF and anti-EGFR for 6 months prior to CRCLM resection) contributed to this trend." (PMID 36691028, 2023). "As well, the lack of in vitro evidence on tumor immunohistochemistry or flow cytometry data of PI3K/AKT pathway and other immunosuppressive genes among EGFR ex20ins patients were considered another limitation." (PMID 35608132, 2023). "The CTCs observed were: 18 CTCs (tumor astrocytes, GFAP+ and/or EGFR-Ki67+), 86 nucleated hematopoietic (nH) cells (non-tumoral cells, CD45+), 12 double-positive cells (dposCTCs) (GFAP+/CD45+ or EGFR-Ki67+/CD45+), and 158 unstained cells (only Hoechst+)." (PMID 37373295, 2023). "EGFR is not overexpressed in A549, in order to make it familiar with the condition of the NSCLC patients (EGFR was expressed in 40–80% of patient tumor tissue)." (PMID 36982500, 2023). "One patient with tumor PD-L1 Tumor cell Proportion Score (TPS) expression >1%, without activating EGFR or ALK alterations, received a programmed death-1 (PD-1) blocker and had stable disease (SD)." (PMID 37342191, 2023). "IHC analyses of tumor tissues showed that afatinib, but not the anti‐CD47 antibody, treatment reduced the levels of EGFR p1068, c‐Src pY416, and CD47 expression." (PMID 37541303, 2023). "Importantly, our data also indicate that the combination of CER-1236 with either a BTK or EGFR inhibitor did not result in toxicity to normal tissues, nor does it affect peripheral blood counts or clotting kinetics, indicating the selectivity of the anti-tumor immune response." (PMID 37194236, 2023). "We added rhCXCL11 and rhEGF to tumor cell with or without anlotinib treatment and found that anlotinib mediated ferroptosis effect is CXCL11 and EGFR independent." (PMID 37283515, 2023). "Nivolumab plus ipilimumab is approved in the United States as first-line treatment for adults with metastatic NSCLC with no EGFR/ALK aberrations and tumor PD-L1 expression ≥ 1%, and in Japan as first-line treatment regardless of tumor PD-L1 expression." (PMID 37548831, 2023). "Histopathological findings were adenocarcinoma, epidermal growth factor receptor (EGFR)–negative, anaplastic lymphoma kinase–negative, and programmed death ligand 1 Tumor Proportion Score 60%." (PMID 37465244, 2023). "In patients with a left-sided primary tumor and wild-type RAS, there was a preference for anti-EGFR therapy regardless of treatment line." (PMID 37760572, 2023). "To determine whether nonengineered tumor lines express sufficiently high levels of tumor-associated surface antigens, we quantified HER2 and EGFR receptor levels on three human cell lines and targeted the split system to HER2 and EGFR (αHER2-Neo2A + αEGFR-Neo2B)." (PMID 36316485, 2023). "EGFR transcripts were higher in the tumours which lacked ER and PR, namely the HER2 positive and TNBC tumours." (PMID 37333824, 2023).